HGF (hepatocyte growth factor)
Diseases named in the same sentence as HGF in open-access papers (continued):
Sharing a sentence is not in itself a finding about the gene and the disease.
tumor (continued). "The HGF/MET axis can modulate the immune suppressive tumor microenvironment (TME), acting at different levels." (PMID 38892318, 2024). "Reduced expression of ST14 slowed tumor growth in mice by impairing the pro-HGF/c-Met signaling pathway and cell proliferation." (PMID 38339272, 2024). "Our recent work shows that tumor ECs undergo a mesenchymal transformation, i.e., Endo-MT, to induce Snail/Slug-dependent aberrant vascularization via HGF/c-Met–, PDGF/PDGFR-β–, and PAK4-mediated mechanisms." (PMID 38416830, 2024). "Mesothelial cells undergo to mesothelial-mesenchymal transition induced by HGF secreted by OC cells, then CAMs promote the expression of pro-tumor factors such as IL-8 and C-X-C motif chemokine ligand 5 (CXCL5) to facilitate dissemination of OC cells." (PMID 39513610, 2024). "Driven by tumor‐derived HGF, tumor‐infiltrating T cells upregulated the expression of programmed cell death protein 1 (PD‐1) after RFA." (PMID 39359691, 2024). "The therapeutic function of ARGX-111 has been validated in HGF-dependent and -independent tumor models in vivo." (PMID 38892318, 2024). "Emerging evidence also suggests an association between tumor microenvironment and MM progression through angiogenesis and stromal interactions, and the efficacy of new agents targeting VEGF and HGF." (PMID 39906669, 2024). "In spite of this, the involvement of the HGF/c-MET signaling axis in remodeling the tumor microenvironment (TME) remains relatively unexplored." (PMID 39201787, 2024). "Hepatocyte Growth Factor (HGF) promotes metastatic potential of the tumor cells to spread in blood circulation via activation of the c-Met pathway." (PMID 38730433, 2024). "It has also been documented that growth factors, e.g., EGF and HGF, induced tyrosine phosphorylation of β-catenin in several tumor cell lines." (PMID 38727316, 2024). "Hepatocyte growth factor/c-mesenchymal epithelial transition factor (HGF/c-Met) signaling mediates the crosstalk between immune-cell and tumor micro-environment." (PMID 38776028, 2024). "As these cells inhibit the proliferation of anti-tumor lymphocytes and expand Treg, the HGF/MET axis significantly contributes to immunosuppression." (PMID 38892318, 2024). "In pancreatic ductal adenocarcinoma [PDAC], pancreatic stellate cells in the tumor microenvironment secrete HGF which activates MET and induces HK2 expression in PDAC cells in a paracrine manner." (PMID 39062731, 2024). "Pancreatic stellate cells (PSCs), which interact with cancer cells, drive tumor growth and metastasis through the HGF/c-MET pathway." (PMID 39664377, 2024). "The tumor stroma is rich in proteases that can convert the inactive, single-chain form of pro-HGF into its active, two-chain form, which can then activate the MET receptor." (PMID 39598385, 2024). "HGF in the tumor microenvironment contributes to tumorigenesis and progression in many human cancers." (PMID 39061147, 2024). "The ARF6 knockout or knockdown of its activator, the guanine exchange factor GRP1, significantly diminishes HGF-dependent angiogenesis and tumor growth in mice." (PMID 39769452, 2024). "HGF is secreted by stromal cells in the tumor microenvironment, and binds to and activates c-MET receptors on the surface of NSCLC cells, initiating a series of downstream signaling pathways such as PI3K/AKT/mTOR, MAPK, and Wnt/β-catenin." (PMID 39201787, 2024). "The MET protein is a receptor tyrosine kinase which upon binding its ligand, hepatocyte growth factor (HGF), mediates tumor cell proliferation, epithelial-mesenchymal transition (EMT), motility, invasion, angiogenesis and metastasis." (PMID 38485737, 2024). "Recent studies have shown that the involvement of the HGF/c-MET signaling pathway within the tumor microenvironment (TME) is multifaceted and paradoxical." (PMID 39201787, 2024).
tumor (continued). "Tumor-associated macrophages produce IGF-1 and hepatocyte growth factor (HGF), determining the proliferation of neoplastic cells and the recruitment of monocytes and the proliferation of neoplastic cells." (PMID 38791916, 2024). "Sunitinib can inhibit programmed death 1 (PD-1) expression in tumor-infiltrating T lymphocytes induced by RFA by inhibiting the hepatocyte growth factor (HGF) and VEGF signalling pathways." (PMID 38495485, 2024). "This antibody demonstrated significant antitumor effects both in vitro and in vivo by inhibiting HGF-mediated tumor growth and enhancing anti-tumor T cell activity." (PMID 39201787, 2024). "Irregular MET activity has been outlined to induce chemoresistance in various cancers and in the maintenance of refractory cancer stem cells, and downregulation of the c-MET/HGF pathway has been reported to reduce cancer stemness and overall tumor growth." (PMID 39458991, 2024). "Regarding tumor immunity, HGF/MET signaling converts M1 macrophages to M2‐like phenotypes, with M2 macrophages promoting HNSCC cell growth." (PMID 39170944, 2024). "cMET, the tyrosine kinase receptor for hepatocyte growth factor (HGF), is known to promote tumor progression and confer resistance to chemotherapy, radiation, and targeted therapies." (PMID 38893082, 2024). "HGF can affect tumor progression through various mechanisms, including modulating the cell growth, migration, and chemoresistance to drugs." (PMID 39201395, 2024). "In some models, Vitamin D supplementation promotes HGF secretion leading to increased senescence and decreased tumor growth." (PMID 39062731, 2024). "Most importantly, MET fusions enable tumor cells to abolish their dependency on the ligand HGF and participate in the autophosphorylation of components in oncogenic cellular pathways." (PMID 38195556, 2024). "Activated CAFs not only produce HGF but also secrete several cytokines, chemokines, and growth factors suitable to recruit and sequester various immune cells into the tumor, acting to maintain poorly inflamed/pro-tumoral environmental conditions." (PMID 38892318, 2024). "Modest decreases in tumor-related cytokines HGF and VEGF were observed in the TCF over treatment cycles (middle)." (PMID 38454126, 2024). "A phase II clinical trial explored the effect of EGCG supplementation on biological markers in patients with prostate carcinoma before surgery, with the results suggesting a substantial reduction in the tumor-promoting HGF and VEGF levels." (PMID 38348027, 2024). "The HGF/c‐Met is considered as biomarker of poor prognosis and tumor aggressiveness in HCC patients." (PMID 38318160, 2024). "For instance, in colon stromal cells, IGF2BP1 functions as a tumor suppressor, and its deletion leads to elevated hepatocyte growth factor levels in the microenvironment." (PMID 39342091, 2024). "HGF/SF has been established in recent investigations to play an important role in GB tumor angiogenesis by boosting endothelial cell proliferation, migration, and survival." (PMID 38523646, 2024). "In lung adenocarcinoma, normal neutrophils were recruited from circulation to the tumor and induced to release active HGF to enhance malignant cell proliferation and migration." (PMID 39061147, 2024). "During this process, there are significant alterations in hepatocyte growth factor (HGF), inflammatory genes, proliferation-related genes, and tumor suppressor genes, all of which contribute to facilitating the growth of residual tumors." (PMID 39276379, 2024). "This dual method of action shows that HGF/SF is important in balancing pro- and anti-angiogenic factors in the tumor microenvironment." (PMID 38523646, 2024). "HGF is a well-characterized angiogenic factor stimulating tumor vascularity by promoting the motility and branching morphogenesis of endothelial cells." (PMID 39302921, 2024).
tumor (continued). "In conclusion, following the paradigm of precision medicine, the accurate evaluation of the HGF/MET axis function in every patient will allow the selection of the optimal MET-targeting immunotherapy approach to obtain the most powerful anti-tumor response." (PMID 38892318, 2024). "HGF is abundant in the TME and is mainly produced and secreted by tumor-associated fibroblasts (CAFs) in addition to being secreted by cancer cells themselves." (PMID 39201787, 2024). "MET and HGF expression have been reported in various NB cell lines, and HGF-mediated cell invasion and angiogenesis were observed in NB tumor models." (PMID 39458991, 2024). "Across various mouse models of cancer, including both HGF-dependent and -independent tumor xenografts, the ADCC-enhanced antibody demonstrated superior efficacy to the ADCC-inactive counterpart." (PMID 39664377, 2024). "Despite the dual roles of HGF/c-Met signaling in neutrophils—both anti-tumor and pro-tumor—the pathway predominantly exerts an immunosuppressive effect on the anti-tumor immune response." (PMID 39201787, 2024). "TAMs also secrete growth factors, including PDGF, EGF, TGF-β, and hepatocyte growth factors (HGF) to induce the proliferation and invasion of tumor cells." (PMID 39003350, 2024). "HGF is its sole ligand and stimulates the EMT in tumor cells and in the crosstalk with cancer-associated fibroblasts (CAFs)." (PMID 39769140, 2024). "The hyperactivity of c-MET and HGF contributes to tumor progression, metastasis, and invasion in various cancers and correlates with advanced cancer stages, poor overall patient survival rate, and prognosis." (PMID 39458991, 2024). "BsAb-5 demonstrated efficacy in inhibiting HGF-mediated tumor development and inducing c-MET degradation, supported by in vitro assays and in vivo xenograft studies." (PMID 39664377, 2024). "In HCC, it is known that both stromal and tumor cells release HGF in the TME, which affects tumor cells through autocrine and paracrine signaling by binding to their c-Met receptors." (PMID 38473265, 2024). "In CRC and BC, MACC1 overexpression regulates β-catenin, HGF/c-Met, and other signaling pathways to elevate tumor malignancy." (PMID 39399490, 2024). "Tumor-stroma interaction correlated with hepatocyte growth factor-phosphatidylinositol-3, 4, 5-triphosphate activation." (PMID 36647832, 2023). "The mesenchymal-epithelial transition factor (c-MET or MET) and hepatocyte growth factor (HGF) signaling pathways play crucial roles in tumor development, survival, metastasis, and acquired treatment resistance." (PMID 37692610, 2023). "Simultaneously, MSCs can also promote the metastasis of tumor cells by secreting cytokines and growth factors (HGF, PDGF, EGF, SDF-1 and TGF-β)." (PMID 37957675, 2023). "Crizotinib inhibits hepatocyte growth factor (HGF), which plays a role in haematopoiesis, and inhibits mesenchymal epithelial growth factor (cMET), which prevents neutrophil recruitment to the tumour." (PMID 37894307, 2023). "It has been shown that CAFs secrete HGF, which leads to tumor cells switching to glycolysis, and tumor cells secrete FGF to “force” CAFs to consume lactate." (PMID 38003931, 2023). "The kringle 1 domain of human HGF a-chain (HGFK1, residues 123–210 of HGF) has been identified as an angiogenic inhibitor, with considerable anti-tumor activity in multiple tumors." (PMID 36094649, 2023). "GC exos carrying hepatocyte growth factor small interfering RNA (HGF siRNA) have been shown to inhibit tumor growth and angiogenesis in nude mice in vivo; human embryonic kidney 293T cells were used as exosome donors." (PMID 37189649, 2023). "Our data suggest that HGF-induced E/M hybrid cells have long-lasting phenotypes of anoikis resistance, migratory, and invasive potential known to support tumor formation." (PMID 36765641, 2023). "Taken together, our findings highlight the potential of targeting the HGF/c-Met pathway to modulate CTL-mediated anti-tumor immunity." (PMID 38137344, 2023).
tumor (continued). "We observed significantly higher Hgf mRNA levels in tumor and normal brain samples than in the cell lines, indicating that HGF is mainly expressed by stroma cells in both, normal brain and tumors." (PMID 36915128, 2023). "Anti-HGF RabMAb not only inhibited the growth of tumor cells, but also inhibited the HGF-dependent proliferation of tumor cells." (PMID 36959792, 2023). "Moreover, the tumor-stroma interaction was associated with higher activation of the hepatocyte growth factor/MET-mediated PI3K/AKT signaling pathway and epithelial-mesenchymal transition process, supporting the hypothesis of fibroblast-involved resistance to EGFR TKI treatment." (PMID 36647832, 2023). "The study confirmed the efficacy and potency of anti-HGF RabMAb in a mouse model of tumor transplantation." (PMID 36959792, 2023). "Hepatocyte growth factor (HGF) combined with c-Met promotes the mitosis of tumor cells, and then induces motility, angiogenesis, migration, invasion and drug resistance." (PMID 36959792, 2023). "Extensive research has established the HGF/c-Met signaling pathway as a promising target for personalized cancer treatment, especially when expressed on tumor cells." (PMID 38137344, 2023). "Here, we report that DA exhibited pro-found anti-tumor effects on human HCC through the suppression of HGF/c-Met signaling cascades in vitro and in vivo." (PMID 37835375, 2023). "The activation of the MET/HGF pathway is a consequence of the tumor microenvironment (TME) that supports tumor growth." (PMID 37835402, 2023). "Abnormal activation of the HGF/c-Met signaling pathway is often accompanied by resistance against anti-tumor treatment and tumor metastasis." (PMID 36094649, 2023). "TGFβ, Fibroblast growth factor 2 (FGF2), matrix metalloproteases 2 (MMP2) and hepatocyte growth factor (HGF) derived from CAF endow tumor cells with stronger proliferative behavior." (PMID 36922546, 2023). "AXL also forms a complex with the non-receptor tyrosine kinase SRC and mediates the enhanced activity of MET in an HGF-independent manner to facilitate tumor migration and invasion in ccRCC." (PMID 36831657, 2023). "In view of the fact that the HGF/MET pathway is relevant in tumor progression and tumorigenesis in diverse types of cancer, it seems obvious that therapeutic approaches are expected to target either the ligand (HGF) or the receptor (MET)." (PMID 37170275, 2023). "The mesenchymal–epithelial transition (MET) gene is an oncogene that encodes RTK, which binds to the hepatocyte growth factor (HGF) and promotes the aggressive nature of the tumours by inducing angiogenesis." (PMID 37760531, 2023). "That study explored the KRAS-specific effect on triggering tumour cell invasion upon fibroblast stimulation through the HGF-c-MET axis." (PMID 38087207, 2023). "GEO database analysis revealed that tumor tissue had lower HGF expression than paired normal tissue in SCLC." (PMID 37828456, 2023). "HGF combined with c-Met promotes the mitosis of various tumor cells, and then induces motility, angiogenesis, migration and invasion." (PMID 36959792, 2023). "HGF immunostaining was considered interpretable when the proportion of tumour cells was sufficient, and positive staining was detected on stromal control cells." (PMID 36799689, 2023). "There is evidence that HGF is one of the key molecules that confer invasive growth potential to tumor cells through tumor-stroma interaction." (PMID 37919751, 2023). "The epigenetic silencing of the miR-144/451a cluster induced by EZH2-catalyzed histone H3K27 methylation increases HGF and MIF expression promoting M2 polarization and the genesis of tumor-associated macrophages (TAMs)." (PMID 37958352, 2023).
tumor (continued). "Then, TANs assist in tumor progression via the production of several cytokines and growth factors involved in tumor growth, including the epidermal growth factor, hepatocyte growth factor, and platelet-derived growth factors (PDGFs)." (PMID 37444436, 2023). "When VEGF is neutralized with bevacizumab, cMET is upregulated, forms homodimers that allow for the binding of HGF, and promotes mesenchymal-like phenotypes and tumor cell invasion." (PMID 37835592, 2023). "Exploring CM content revealed the enrichment of a number of soluble factors in the tumor-activated HS-5, such as soluble uPAR (SuPAR), IL-6, and hepatocyte growth factor (HGF)." (PMID 37175439, 2023). "The MSCs increased in vivo tumor growth and also increased intra-tumoral expression of bFGF, TGFβ1, hepatocyte growth factor (HGF), MMP2, and MMP9." (PMID 37569686, 2023). "For example, in bronchoalveolar carcinoma, the cytokines released by tumor cells caused the neutrophils to release hepatocyte growth factor (HGF), which then increased tumor cell migration and spread." (PMID 36661709, 2023). "These can be caused by activating mutations in the kinase domain or, more commonly, MET gene amplification, and can lead to HGF‐independent cellular proliferation and tumour growth." (PMID 36799689, 2023). "Using a semiquantitative scoring (see Section 2), HGF expression was detected in the cytoplasm of the tumour cells in eight of 12 interpretable samples." (PMID 36799689, 2023). "Plasma levels of human HGF correlated directly with U87 MG/HNR xenograft tumor mass, consistent with a prior report for U87 MG." (PMID 36672409, 2023). "The hepatocyte growth factor (HGF)/c-Met pathway contributes to tumor invasion and metastasis and is an essential factor in the progression and prognosis of BC patients." (PMID 38132441, 2023). "HGFAC is a novel serine protease that activates the precursor of hepatocyte growth factor and promotes angiogenesis, tumorigenesis, and regeneration in the tumor microenvironment." (PMID 38077422, 2023). "In this way, we evaluated the contribution of the HGF/MET axis to cancer cell dissemination independently of its direct activities in cells of the tumor microenvironment." (PMID 37345079, 2023). "These HGF molecules from CAFs activate c-Met in neighboring tumor cells via paracrine signaling in a 2:2 manner." (PMID 37919751, 2023). "Studies have shown that this inhibitor only reduces tumor growth and metastasis by about 60%, and HGF-c-Met signaling is only one of the oncogenic signaling pathways that promote tumorigenesis." (PMID 37529603, 2023). "Both hypoxia and sublethal hyperthermia after ablation were found to stimulate tumor cells and stromal cells to produce HGF in the residual tumor." (PMID 36831664, 2023). "It is well known that cytokines secreted by CAFs play a significant role in tumor growth; among these cytokines, HGF is secreted mainly by CAFs and acts on MET-positive cancer cells in the tumor microenvironment." (PMID 37887325, 2023). "Neutrophil was an inflammatory cell that promoted tumor development by secreting several factors such as hepatocyte growth factor, transforming growth factor‐β, and vascular endothelial growth factor." (PMID 36114787, 2023). "The possible mechanisms by which neutrophils promote tumor progression include changes in the microenvironment shaped by cancer cells and release of some growth factors, such as epidermal growth factor and hepatocyte growth factor." (PMID 36937347, 2023). "Hepatocyte growth factor (HGF) is a cytokine secreted by stromal cells in the tumor microenvironment and binds to “mesenchymal-epithelial transition (c-MET) factor,” which is a proto-oncogenic receptor and activates the HGF/c-MET signaling pathway." (PMID 36789987, 2023). "mRNA expression of 16 soluble factors was quantified with tumor cell density, and we found that IL-8 was the only factor with fluctuations (HGF, IL-1A, and IL-12B expression levels were extremely low)." (PMID 36932390, 2023).